POLQ (DNA polymerase theta)
Description:
Low-fidelity DNA polymerase with a putative helicase activity that promotes microhomology-mediated end-joining (MMEJ), an alternative non-homologous end-joining (NHEJ) machinery required to repair double-strand breaks in DNA during mitosis. MMEJ is an error-prone repair pathway that produces deletions of sequences from the strand being repaired and promotes genomic rearrangements, such as telomere fusions, some of them leading to cellular transformation. MMEJ is required during mitosis to repair persistent double-strand breaks that originate in S-phase. Although error-prone, MMEJ protects against chromosomal instability and tumorigenesis (By similarity). The polymerase acts by binding directly the 2 ends of resected double-strand breaks, allowing microhomologous sequences in the overhangs to form base pairs. It then extends each strand from the base-paired region using the opposing overhang as a template. Requires partially resected DNA containing 2 to 6 base pairs of microhomology to perform MMEJ. The polymerase lacks proofreading activity and is highly promiscuous: unlike most polymerases, promotes extension of ssDNA and partial ssDNA (pssDNA) substrates. When the ends of a break do not contain terminal microhomology must identify embedded complementary sequences through a scanning step. Promotes dissociation of the replication protein A complex (RPA/RP-A), composed of RPA1, RPA2 and RPA3, from resected double-strand breaks to allow their annealing and subsequent joining by MMEJ. Removal of RPA/RP-A complex proteins prevents RAD51 accumulation at resected ends, thereby inhibiting homology-recombination repair (HR) pathway. Also shows RNA-directed DNA polymerase activity to mediate DNA repair in vitro; however this activity needs additional evidence in vivo. May also have lyase activity. Involved in somatic hypermutation of immunoglobulin genes, a process that requires the activity of DNA polymerases to ultimately introduce mutations at both A/T and C/G base pairs (By similarity). POLQ-mediated end joining activity is involved in random integration of exogenous DNA hampers. DNA helicase activity has been examined and has and has not been demonstrated.
Synonyms: POLH; PRO0327
Tractability: Small molecule: a structure with a bound ligand is known. PROTAC: ubiquitination databases record sites on it.
Target class: Enzyme; Transferase
Chemical probes: ART558 (high quality)
Gene: Protein-coding gene on chromosome 3 (121,431,426 to 121,546,002, reverse strand). Ensembl gene ENSG00000051341.
Subcellular location: Nucleus; Chromosome
Subcellular location (Human Protein Atlas): Nucleoplasm; Cytosol; Golgi apparatus
Pathways (Reactome):
DNA Repair: HDR through MMEJ (alt-NHEJ)
Gene Ontology:
Molecular function: 5'-deoxyribose-5-phosphate lyase activity; ATP hydrolysis activity; chromatin binding; DNA helicase activity; DNA polymerase activity; DNA-directed DNA polymerase activity; magnesium ion binding; protein binding; single-stranded DNA helicase activity; damaged DNA binding; RNA-directed DNA polymerase activity; 3'-5' DNA helicase activity; ATP binding; DNA binding; nucleic acid binding
Biological process: base-excision repair; DNA damage response; double-strand break repair; double-strand break repair via alternative nonhomologous end joining; error-prone translesion synthesis; negative regulation of double-strand break repair via homologous recombination; protein homooligomerization; replication fork processing; DNA repair; somatic hypermutation of immunoglobulin genes; DNA replication; DNA-templated DNA replication; RNA-templated DNA biosynthetic process
Cellular component: chromosome; mitochondrial nucleoid; nucleoplasm; nucleus; site of DNA damage; site of double-strand break
Genetic constraint (gnomAD): Loss-of-function variants: 153 observed, 170.46 expected, observed/expected ratio (o/e) 0.9, 90% interval 0.79 to 1.03. The upper end of that interval is the gene's LOEUF score, 1.03, which puts it in group 4 of 6, group 1 being the genes least tolerant of losing a copy. Missense variants: 2,155 observed, 2,373.9 expected, observed/expected ratio (o/e) 0.91, 90% interval 0.88 to 0.94. Synonymous variants: 762 observed, 832.39 expected, observed/expected ratio (o/e) 0.92, 90% interval 0.86 to 0.97.
Cancer hallmarks: genome instability and mutations (promotes); genome instability and mutations (suppresses); proliferative signalling (promotes)
Homologues: Orthologues: chimpanzee POLQ (99% identical), macaque POLQ (96% identical), dog POLQ (80% identical), rabbit POLQ (80% identical), pig POLQ (76% identical), mouse Polq (73% identical), rat Polq (72% identical), tropical clawed frog polq (52% identical), zebrafish polq (45% identical), Drosophila melanogaster PolQ (26% identical), Caenorhabditis elegans polq-1 (20% identical). Paralogues in human: ASCC3 (11% identical), HELQ (11% identical), SNRNP200 (11% identical), MTREX (8% identical), SKIC2 (8% identical), HFM1 (8% identical), DDX60 (7% identical), DDX60L (7% identical).
Diseases named in the same sentence as POLQ in open-access papers:
POLQ is named in the same sentence as 64 diseases in open-access papers, as found by Europe PMC text mining. Sharing a sentence is not in itself a finding about the gene and the disease. The quoted sentences say what the papers report.
breast carcinoma (25 papers, 2010 to 2025). "Compared to normal tissues, POLQ expression is significantly upregulated in breast cancer tissues, and high expression of POLQ is associated with poor clinical prognosis, with a 4.3-fold increased risk of death in patients with high POLQ expression." (PMID 39768855, 2024). "Several studies have indicated that POLQ is highly expressed in human cancers, and its overexpression is linked to poor survival outcomes in breast cancer." (PMID 39046429, 2024). "In breast cancer and colon cancer, POLQ is associated with the upregulation of genome stability genes and replication initiation proteins such as CDC6, CDT1, and CDC45." (PMID 38270643, 2024). "In fact, the overexpression of POLQ in cases of colorectal, gastric, lung and breast cancers are associated with a worse overall survival." (PMID 34201502, 2021). "Recently, in the context of mammary cancer, high POLQ expression was observed in the most genomically unstable breast cancer subgroup containing HR-deficient tumors." (PMID 34458275, 2021). "Other case–control studies also associated missense POLQ variants with an increased risk of breast cancer." (PMID 34357098, 2021). "Several POLQ SNPs have also been associated with a risk of different tumors, such as breast cancer, esophageal cancer, and Non-Hodgkin’s Lymphoma." (PMID 30591675, 2018). "This is the first study to demonstrate that POLQ overexpression is associated with an extremely poor outcome in breast cancer on both univariate and multivariate analysis." (PMID 20700469, 2010). "This identified a total of 97 genes that were strongly associated with POLQ overexpression in breast cancer." (PMID 20700469, 2010). "We also analysed the pathways associated with POLQ expression in vivo by data-mining gene expression data from published breast cancer studies (n=1015 samples)." (PMID 20700469, 2010). "Additionally we observed one mutation in IKZF3 (found also as often occuring in HER2+ cancers, as in our cohort) and in POLQ associated with poor prognoses in breast cancer patients." (PMID 41256402, 2025). "Lemée found that POLQ was significantly up-regulated in breast cancer tissues, and the up-regulation of POLQ expression level was associated with poor prognosis of patients (the risk of death in patients with high POLQ expression was 4.3 times higher than that in patients with low expression)." (PMID 39520627, 2024). "Reanalysis of publicly available cancer genomic data also suggested that of the four cancer histotypes that commonly exhibit pathogenic BRCA1/2 mutations, BRCA-mutant breast cancers tended to express higher POLQ mRNA than for BRCA-gene wild type breast cancers." (PMID 34140467, 2021). "Given the importance of DNA polymerase POLQ as genetic signature for the development and progression of breast cancer, the analysis of genetic variants in the POLQ gene represents a yet poor explored field of potential biomarkers in patients with breast cancer." (PMID 25409685, 2014). "The whole sequencing of POLQ gene and its untranslated regions would also be fundamental to determine whether these inherited genetic variations can predispose women to breast cancer, and particularly to bilateral breast cancer." (PMID 25409685, 2014). "POLQ associated radioresistance is likely to contribute to these findings and further work is required to assess whether POLQ expression increases the tumour cell resistance to the cytotoxic and endocrine treatments typically used to treat breast cancers." (PMID 20700469, 2010). "Previous literature reports have indicated that POLQ promotes cell growth and malignant progression in various cancers, including liver cancer, cervical cancer, breast cancer, and colon cancer." (PMID 38270643, 2024). "Another study on breast cancer has confirmed that high POLQ expression can serve as an independent prognostic factor for breast cancer, indicating a poorer prognosis." (PMID 39768855, 2024).
breast carcinoma (continued). "Recent studies have shown that POLQ is significantly up-regulated in hepatocellular carcinoma, lung cancer, breast cancer, ovarian cancer, prostate cancer and other malignant tumors, and is closely related to poor clinical outcomes of patients." (PMID 39520627, 2024). "One study reported suppression of POLQ expression by binding the transcription factor zinc finger E-box binding homeobox 1 (ZEB1) to the POLQ promoter in breast cancer cells." (PMID 36835031, 2023). "The upregulation of POLQ in breast cancer was deduced to play a great role in increasing intrinsic radio-sensitivity." (PMID 34517891, 2021). "A complementary body of literature reported an upregulation of POLQ in different tumor tissues (breast cancer, non-small cell lung cancer, oral squamous cell carcinoma, stomach cancer, and CRC), and this overexpression acted as a strong prognostic factor." (PMID 30591675, 2018). "The DNA polymerase theta encoded by POLQ, has been previously associated with radiotherapy resistance, leading to poorer prognosis in luminal breast cancers." (PMID 27341628, 2016). "Further analysis to explain the functional consequences of POLQ c.-1060GG on YY1-mediated POLQ expression and on breast cancer progression are warranted." (PMID 25409685, 2014). "The objective of this study was to analyze genetic variants related to POLQ as new population biomarkers of risk in hereditary (HBC) and sporadic (SBC) breast cancer." (PMID 25409685, 2014). "Here, we evaluated the possible contribution of nine SNPs in the POLQ gene to the development of both sporadic and hereditary breast cancer through a case–control approach." (PMID 25409685, 2014). "We therefore correlated the clinical outcomes of two retrospective series of patients with early breast cancer with the expression levels of POLQ, as determined by microarray gene expression analysis." (PMID 20700469, 2010). "Several other gene signatures have been discovered and validated to have prognostic significance for breast cancer, so is POLQ better or different?" (PMID 21301045, 2010). "In order to identify genes which were co-expressed with POLQ, a seed-clustering analysis was performed on gene expression data obtained from five different breast cancer data sets." (PMID 20700469, 2010). "We therefore correlated the clinical outcomes of two series of breast cancer patients (n=279 in total) with the expression levels of POLQ as determined by microarray gene expression analysis." (PMID 20700469, 2010). "In this issue of Oncotarget, Higgins and colleagues describe another prognostic gene signature for breast cancer, this one being particularly unusual in containing just a single gene, POLQ (official name: polymerase DNA directed theta)." (PMID 21301045, 2010). "POLQ variants, a DNA polymerase with helicase activity involved in DNA repair, have been reported in early-onset breast cancer women, and seem to be associated (but not confirmed) to CRC risk." (PMID 40429818, 2025). "POLQ exhibits elevated expression levels in diverse malignant tumor tissues, such as lung adenocarcinoma, gastric cancer, colorectal cancer, breast cancer, cervical cancer, and oral cancer, and its presence has been linked to unfavorable prognostic outcomes in a number of tumors." (PMID 38270643, 2024). "The DNA polymerase theta (Polθ)-mediated end joining (TMEJ) pathway for repair of chromosomal double strand breaks (DSBs) is essential in cells deficient in other DSB repair pathways, including hereditary breast cancers defective in homologous recombination." (PMID 35927262, 2022). "A POLQ germline variant of unknown significance, as in the presented family, has already been reported in non-BRCA1/BRCA2-mutated breast cancer families." (PMID 34357098, 2021). "Moreover, POLQ expression level is low in all CL tumors as compared to other breast cancer subtypes." (PMID 34458275, 2021).
breast carcinoma (continued). "In HR-proficient background, inactivation of POLQ increased cell death in ATR-deficient cells and sensitized breast cancer cells overexpressing POLQ to DNA damaging agents that cause replication stress (camptothecin and etoposide) or fork collapse (ATR inhibitors)." (PMID 34201502, 2021). "further demonstrate that genetic alterations in PolqSL genes could be observed in around 30% of TCGA breast cancer samples, indicating that inhibiting POLQ could be a promising therapeutic strategy for breast cancer treatment." (PMID 34517891, 2021). "We observed significantly higher levels of POLQ mRNA in breast cancers with PolqSL gene alteration." (PMID 31537809, 2019). "Here we showed that a specific SNP in the promoter region of POLQ is associated the phenotype of hereditary breast and ovarian cancer syndrome and/or with bilateral breast cancer, but not sporadic breast cancer." (PMID 25409685, 2014). "Interestingly, patients with a more aggressive phenotype of breast cancer (triple negative), also had the highest levels of POLQ expression and lower survival (OR = 4.28; p = 0.0001), regardless of the levels of CYCLIN E and number of positive nodes." (PMID 25409685, 2014). "In this study we have demonstrated that POLQ is frequently upregulated in breast cancers." (PMID 20700469, 2010). "Moreover, approximately 30% of ductal carcinoma and lobular carcinoma breast cancers have genetic alterations in synthetic lethality POLQ gene partners and show enhanced Pol θ/TMEJ activity, thereby suggesting that Pol θ inhibition is a promising therapeutic strategy." (PMID 36835031, 2023). "Further characterization of upcoming ZEB1-expressing tumor cells is needed to confirm this hypothesis, but one may suggest that ZEB1 and POLQ have opposite and complementary roles in the control of both the stability and integrity of breast cancer cell genomes." (PMID 34458275, 2021). "We analyzed through case–control study nine SNPs of POLQ in hereditary (HBC) and sporadic (SBC) breast cancer patients using Taqman Real Time PCR assays." (PMID 25409685, 2014). "POLQ is not essential for normal cell survival, but is over-expressed in about 70% of breast cancers regardless of HR status." (PMID 33963218, 2021). "Taken into account the possible involvement of POLQ in single and/or DSB repair, we hypothesized that variations in this DNA repair gene could drive the development of breast cancer." (PMID 25409685, 2014). "Although POLQ overexpression has previously been demonstrated in lung, gastric and colorectal cancers, to the best of our knowledge, this has not previously been shown in breast cancer." (PMID 20700469, 2010).
lung carcinoma (10 papers, 2016 to 2025). "The present study is the first to show concurrent overexpression of POLQ and PLK4 at both the mRNA and protein level in LAC, and also induction of centrosome amplification in lung cancer cells associated with POLQ and PLK4 overexpression." (PMID 31137743, 2019). "Several studies have shown the association of POLQ expression with outcome in other tumor entities such breast cancer, ovarian colorectal cancer or lung cancer, and also its relation with pathogenesis in lung adenocarcinoma, hepatocellular carcinoma and esophageal squamous cell carcinoma." (PMID 39435280, 2024). "In addition, lung cancer cells with higher POLQ expression levels showed a higher frequency of mutations induced by UV irradiation and Tg introduction." (PMID 31137743, 2019). "Elevated expression of POLQ has been observed in various tumor tissues, such as lung cancer, colon cancer, and gastric cancer, where it contributes to maintaining genome stability and correlates with poor patient prognosis." (PMID 38270643, 2024). "We established H1299 lung cancer cell lines capable of inducibly expressing the POLQ protein and control H1299 cell lines using the PiggyBac transposon vector system, and performed three kinds of experiments using these cell lines." (PMID 31137743, 2019). "When H1299 lung cancer cell clones overexpressing POLQ were established and examined for their malignant potential, the clones showed greater resistance to a DSB-inducing chemical and an increased number of mutations." (PMID 31137743, 2019). "When H1299 human lung cancer cell clones overexpressing POLQ were established and examined, the clones showed resistance to a DSB-inducing chemical in the clonogenic assay and an increased frequency of mutations in the supF forward mutation assay." (PMID 31137743, 2019). "First, we established H1299 lung cancer cell lines capable of inducibly expressing the POLQ protein and control H1299 cell lines using the PiggyBac transposon vector system." (PMID 31137743, 2019). "Here, we show that expression of translesion synthesis (TLS) polymerase Q (POLQ) was significantly elevated by exposure of lung cancer cells A549/DR (a cisplatin-resistant A549 cell line) to cisplatin." (PMID 27533083, 2016). "Since PLK4 is known to be involved in centrosome regulation, we then investigated whether the number of centrosomes was dysregulated in the lung cancer cells showing concurrent overexpression of POLQ and PLK4." (PMID 31137743, 2019). "Furthermore, POLQ overexpression was found to be concurrently associated with Polo Like Kinase 4 (PLK4) overexpression, which was also examined in the lung cancer cell clones." (PMID 31137743, 2019). "We next planned to investigate the effects of POLQ overexpression in human lung cancer cells." (PMID 31137743, 2019). "Interestingly, we found that POLQ expression in breast, colorectal and lung cancers is positively correlated with the expression of 15 out of 64, 9 out of 61 and 15 out of 92 genes, respectively." (PMID 27612511, 2016). "The higher expression of POLQ mRNA observed in breast, colorectal and lung cancer, correlates with reduced patient survival, and may be helping cancer cells to counteract replication stress and genome instability, preventing large deletions and genomic rearrangements." (PMID 39435280, 2024). "Moreover, POLQ overexpression was found to be associated with advanced pathologic stage, increased somatic mutation load, and PLK4 overexpression in lung adenocarcinoma, thus inducing centrosome amplification, indicating the potential involvement of POLQ in the development of lung cancer." (PMID 34517891, 2021).